EEF2 (eukaryotic translation elongation factor 2)
Diseases named in the same sentence as EEF2 in open-access papers (continued):
Sharing a sentence is not in itself a finding about the gene and the disease.
non-small cell lung carcinoma (6 papers, 2021 to 2026). A group of at least three distinct histological types of lung cancer, including non-small cell squamous cell carcinoma, adenocarcinoma, and large cell carcinoma. "In non-small cell lung cancer, eEF2 was reported to contribute to cancer cell invasion through interacting with arginine methyltransferase 7, yet its detailed molecular function was not deeply investigated." (PMID 37088855, 2023). "High expression of lncRNA MALAT1 in non-small cell lung cancer accelerated tumorigenesis via adsorbing miRNA-515-5p and then upregulating EEF2 protein levels." (PMID 37612724, 2023). "The interaction between Hspa5 and EEF2 promotes the overexpression of PRMT7 in non-small cell lung cancer cells, thus regulating cancer cell migration and colony formation." (PMID 34437425, 2021). "eEF2 peptide levels increased, with elevated eEF2 protein demarking non-small cell lung cancer." (PMID 34711247, 2021). "In non-small-cell lung cancer, the overexpressed protein arginine methyltransferase 7 (PRMT7) could interact with eEF2, thus promoting the cell metastasis." (PMID 39707196, 2024).
prostate carcinoma (6 papers, 2014 to 2022). A carcinoma that arises from epithelial cells of the prostate gland. "Immunohistochemistry experiments showed that the eEF2 protein was overexpressed in the majority of lung, esophageal, pancreatic, breast and prostate cancers, HNSCC, glioblastoma multiforme and non-Hodgkin’s lymphoma (NHL)." (PMID 24589652, 2014). "Furthermore, the relative phosphorylation of eEF2 at T56 in DU145 prostate cancer cells was less affected by treatment of TGF-β1 even in the presence of CQ and consequently Vimentin was similarly expressed in response to TGF-β1." (PMID 36230768, 2022). "Both EEF2 and FLNC were associated with the formation of prostate cancer." (PMID 34437425, 2021).
Alzheimer disease (5 papers, 2015 to 2025). A progressive, neurodegenerative disease characterized by loss of function and death of nerve cells in several areas of the brain leading to loss of cognitive function such as memory and language. "Cross‐species analysis combining C. elegans proteomics and Alzheimer's disease brain transcriptomics reveals shared alterations in stress response, metabolism, and protein homeostasis, highlighting eEF‐2 as a conserved key regulator." (PMID 40653809, 2025). "High levels of phosphorylated eEF2 have been described in Alzheimer disease, Parkinson disease and genetic epilepsy and it has also been reported that inhibition of eEF2K activity ameliorate the pathology." (PMID 34980259, 2022). "In addition, high levels of p-eEF2 were also reported in a mouse model of Alzheimer’s disease and in brain material of patients affected by Alzheimer’s disease, suggesting a particular role of the eEF2K/eEF2 pathway in mental disorders." (PMID 27826228, 2016). "In addition, eEF1A, along with eEF2, has been shown to be related to neurodegenerative disorders including Alzheimer disease (AD) and Parkinson disease (PD) with an unknown mechanism." (PMID 35127825, 2021).
Cognitive impairment (5 papers, 2020 to 2026). Abnormal cognition is characterized by deficits in thinking, reasoning, or remembering. "Hyperphosphorylation of eEF2 is linked to many neuronal diseases characterized by cognitive impairments." (PMID 41896174, 2026). "Here, we investigated the roles of neuronal eukaryotic elongation factor 2 (eEF2) phosphorylation (by its kinase eEF2K) in AD-associated cognitive deficits and NPS." (PMID 41836505, 2026). "Interestingly, our data suggested a role of PQBP1 dysregulation in DS‐associated eEF2 hyperphosphorylation and cognitive deficits." (PMID 38934363, 2024). "We next investigated whether upregulation of PQBP1 expression could alleviate DS‐associated eEF2 hyperphosphorylation and cognitive impairment." (PMID 38934363, 2024). "Inhibition of eEF2 phosphorylation through genetic or pharmacological approaches improved multiple aspects of DS‐associated pathophysiology including protein synthesis deficiency, synaptic failure, and cognitive impairments." (PMID 38934363, 2024). "Inhibition of eEF2 phosphorylation through suppression of eEF2K in DS model mice improved multiple aspects of DS‐associated pathophysiology including de novo protein synthesis deficiency, synaptic morphological defects, long‐term synaptic plasticity failure, and cognitive impairments." (PMID 38934363, 2024). "Recent studies suggest a link between eEF2 hyper-phosphorylation and several neuronal diseases characterized by cognitive impairments." (PMID 41392093, 2025). "From a translational perspective, inhibition of eEF2K and eEF2 phosphorylation can be an appealing therapeutic approach for aging‐related cognitive deficits in DS." (PMID 38934363, 2024). "In summary, suppression of eEF2K can restore eEF2 phosphorylation levels and alleviate cognitive deficits in the Ts65Dn DS mouse model." (PMID 38934363, 2024). "In brief, treatment of eEF2K inhibitors could decrease eEF2 phosphorylation, boost de novo protein synthesis, reverse synaptic impairments, and rescue cognitive deficits in Ts65Dn DS model mice." (PMID 38934363, 2024). "Importantly, restoration of eEF2 phosphorylation by suppression of eEF2K could alleviate multiple pathophysiological abnormalities and improve aging‐related cognitive deficits in two different lines of a DS mouse model." (PMID 38934363, 2024).
esophageal cancer (5 papers, 2014 to 2024). A primary or metastatic malignant neoplasm involving the esophagus. "In the study, eEF2 was highly expressed in esophageal cancer and knocking down of eEF2 suppress tumor cell proliferation and colony formation." (PMID 39707196, 2024). "The results showed that EEF2 protein is highly expressed in normal esophageal tissues but moderately expressed in esophageal cancer tissues." (PMID 34568328, 2021). "Additionally, we found that TSN impedes the growth of esophageal cancer via targeting eEF2 and downregulating the protein synthesis of topoisomerase I and II." (PMID 39707196, 2024). "eEF2 was reported to be highly expressed in esophageal cancer and endometrial carcinoma; however, its contributing role in these cancers is still unknown." (PMID 37088855, 2023).
gastric cancer (5 papers, 2014 to 2024). A primary or metastatic malignant neoplasm involving the stomach. "Enzyme-linked immunosorbent assay showed that serum eEF2 IgG Ab levels were significantly higher in colorectal and gastric cancer patients compared to healthy individuals." (PMID 24589652, 2014). "In the present study, we showed the elevation of serum EF2 IgG levels in colorectal and gastric cancer patients, indicating that eEF2 overexpressed in cancer cells was recognized by the host immune system and induced eEF2-specific immune responses." (PMID 24589652, 2014). "eEF2 IgG Ab levels were significantly (p<0.01) higher in both colorectal and gastric cancer patients than healthy individuals." (PMID 24589652, 2014). "The production of eEF2 IgG autoantibody was enhanced in patients with colorectal and gastric cancer and 9-mer eEF2 peptides elicited EF2-specific CTLs from healthy donors." (PMID 24589652, 2014). "Serum eEF2 IgG Ab levels were examined by ELISA in 79 colorectal and 80 gastric cancer patients and 40 healthy individuals and detected in all the samples examined." (PMID 24589652, 2014). "Various experiments have proved that EEF2 may be the direct target regulated by Mir-183-5P in gastric carcinoma (GC)." (PMID 34437425, 2021). "eEF2 IgG Ab levels ranged from 7.8 to 301.7 (median 41.1), from 8.1 to 353.9 (median 33.6) and from 5.2 to 53.0 (median 20.6) ERU in colorectal and gastric cancer patients and healthy individuals, respectively." (PMID 24589652, 2014). "The hub proteins identified, CAT, PLEKHA4, HSP90AB1, TXN, EEF2, H6PD, and PDIA3, may play important roles in the treatment of gastric cancer using nintedanib." (PMID 38406279, 2024).
leukemia (5 papers, 2019 to 2023). A malignant (clonal) hematologic disorder, involving hematopoietic stem cells and characterized by the presence of primitive or atypical myeloid or lymphoid cells in the bone marrow and the blood. "In addition to Myc and Bcl2, other tumor-promoting genes such as Eef2 and Myh10 were upregulated in leukemia cells, whereas tumor suppressors such as Ikzf1, Ikzf2, Arid1b, Arid2, Samhd1, Bach2, and Myo18b were downregulated." (PMID 34907175, 2021). "First, denileukin diftitox, an antineoplastic agent used to treat leukemia and lymphoma, inhibits protein synthesis by ADP ribosylation of elongation factor 2 (eEF2), resulting in cell death." (PMID 35013211, 2022).
lung adenocarcinoma (5 papers, 2014 to 2024). A carcinoma that arises from the lung and is characterized by the presence of malignant glandular epithelial cells. "Overexpression of EEF2 was associated with disease progression of lung adenocarcinoma cells." (PMID 34721517, 2021). "Recent studies have shown that eEF2 is overexpressed in several cancers, including gastrointestinal cancers and lung adenocarcinoma, where elevated levels correlate with increased tumor incidence and poorer patient prognosis." (PMID 39707196, 2024). "In lung adenocarcinoma cells, the SUMOylation of eukaryotic elongation factor 2 (eEF2) has been found to be crucial for protein stability and anti-apoptotic action." (PMID 36675915, 2023). "Methylation of eEF2 at lysine 525 (eEF2K525me3), catalyzed by FAM86A, is crucial for mRNA translation and tumor progression in lung adenocarcinoma (LUAD)." (PMID 39707196, 2024).
Spinocerebellar Ataxia (5 papers, 2016 to 2025). "We also analyzed the co-expression network of those ataxia risk genes and revealed a central role of Eef2, Grid2, Tubb4a in the co-expression networks, while Ttbk2 and Bean1 have few interactions with other ataxia risk genes." (PMID 30690467, 2019). "We analyzed the expression pattern of 28 ataxia risk genes and found that majority of them are highly expressed in PCs, while only a few of them, including elongation factor 2 (Eef2), ataxin-10 (Atxn10), nucleolar protein 56 (Nop56), are widely expressed in all cell types." (PMID 30690467, 2019). "The affected proteins/disorders included Atp2a2 (Darier’s disease), Eef2 and Itpr1 (Spinocerebellar ataxia), Atp1a3 (Dystonia Parkinsonism)." (PMID 28893375, 2017).
viral infection (5 papers, 2023 to 2025). "We found that at 10 hpi, the C7/10-derived virus infection led to a significantly higher proportion of phosphorylated eEF2 compared to total eEF2." (PMID 37632027, 2023). "To add to this, when comparing the relative amount of phosphorylated eEF2 to that of eEF2, we found a 2.6-fold increase in the ratio in C7/10-derived virus infection compared to that of the BHK-derived virus infection." (PMID 37632027, 2023). "To analyze the role of the interacting proteins during viral infection, we examined previously published proteomic databases and found that EEF2, ANXA1, ANXA5, SLADRA, CLTA, and FTH1 were significantly enriched and FTH1 was notably upregulated in ASFV-infected PAMs." (PMID 40661982, 2025). "The continued downregulation of structural genes like ITGB4 and metabolic genes like EEF2 across different viruses could reflect a sustained reprogramming of cellular processes in the extended phase of viral infection." (PMID 38655085, 2024). "Finally, we show that the C7/10-derived virus infection of HEK-293 cells leads to elevated levels of phosphorylated eukaryotic translation elongation factor-2 (eEF2), identifying a potential mechanism leading to the more rapid shut-off of host translation." (PMID 37632027, 2023). "Since eEF2 phosphorylation was induced by virus infection, we hypothesized that it might be part of an innate immune response that is triggered by the sensing of certain pathogen-associated molecular patterns (PAMPs), e.g. viral dsRNA replication intermediates, via the RIG-I/MDA5-MAVS pathways." (PMID 36848386, 2023). "To explore the relationship between eEF2 phosphorylation and NFE2, we employed an in vitro mouse fetal liver cell (FLC) culture system, a highly efficient platform for gene manipulation via viral infection." (PMID 40429942, 2025).
glioblastoma (4 papers, 2014 to 2025). The most malignant astrocytic tumor (WHO grade IV). "Glioblastoma and glioma dataset revealed that EEF1A1, EEF1G, EEF1D and EEF2 were significantly overexpressed in tumor tissues whereas EEF1A2 was significantly downregulated." (PMID 29342219, 2018).
glioma (4 papers, 2010 to 2024). A benign or malignant brain and spinal cord tumor that arises from glial cells (astrocytes, oligodendrocytes, ependymal cells). "There is evidence that CaM-dependent phosphorylation of eEF2 is associated with cell proliferation in rat glia and gliomas." (PMID 21060779, 2010). "In gliomas, an important factor of anoikis resistance is elongation factor-2 kinase (eEF2), which contributes to the malignant phenotype of glioblastomas by promoting glioma cell migration and invasion." (PMID 39062119, 2024).
lymphoma (4 papers, 2015 to 2025). A malignant (clonal) proliferation of B- lymphocytes or T- lymphocytes which involves the lymph nodes, bone marrow and/or extranodal sites. "We observed that feeding lymphoma-bearing mice with a Low CHO diet resulted in AMPK activation, mTOR and eEF2 inhibition indicating a block in protein translation." (PMID 27689327, 2016).
melanoma (4 papers, 2017 to 2025). A malignant, usually aggressive tumor composed of atypical, neoplastic melanocytes. "The compound NH125, which not only is an EEF2K inhibitor but can promote EEF2 phosphorylation to regulate protein translation, demonstrated a similar pattern of inhibiting both cholesterol metabolism and proliferation of melanoma cells." (PMID 35408842, 2022).
endometrial cancer (3 papers, 2021 to 2024). Primary or metastatic malignant neoplasm involving the endometrium (mucous membrane that lines the endometrial cavity). "Differentially expressed proteins were allocated in KEGG pathways, identifying CCT7, HSPA8, PCBP2, LONP1, PFN1 and EEF2 as highly expressed in endometrial cancer." (PMID 39194522, 2024). "EEF2 was further validated to be decreased in Black endometrial cancer patients (irrespective of histology type) in reverse phase protein array (RPPA) TCGA data." (PMID 33920951, 2021).
liver cancer (3 papers, 2015 to 2024). An epithelial or non-epithelial malignant neoplasm that arises from the liver. "We also examined the top most informative features and observed that the most informative nullomers were found at liver cancer-associated genes, including FTH1, EEF2, TMSB10, ACTB and the long non-coding RNA MALAT among others." (PMID 38351138, 2024). "Whether the crotonylation of CAT, S100A8, and EEF2 plays a vital role in liver cancer proliferation and the cellular response to hypoxia remains to be investigated." (PMID 35977926, 2022). "We then took an intersection of the Kcr proteins identified in liver cancer tissue quantitative analysis and hypoxic cell lines: CAT, S100A8, EEF2, and LMNA were co-identified." (PMID 35977926, 2022).
myocardial ischemia (3 papers, 2017 to 2024). A disorder of cardiac function caused by insufficient blood flow to the muscle tissue of the heart. "Furthermore, overexpression of eEF2 contributes to the inhibition of cardiomyocyte apoptosis during myocardial ischemia reperfusion via upregulating Bcl-2 expression." (PMID 30987676, 2019). "Previous studies have also demonstrated that eEF2 is inhibited during myocardial ischemia." (PMID 28427148, 2017).
neuroblastoma (3 papers, 2014 to 2021). Neuroblastoma (NB) is the most common solid, extracranial childhood tumor. "Other proteins linked to metabolism such as eEF2, PFKP, GAPDH and ribosomal protein L10a were also confirmed to be enriched in the EVs secreted by MYCN-positive neuroblastoma cells." (PMID 34847775, 2021). "We used shRNA knockdown of EEF2 mRNA, reducing its steady‐state level by 33% to attenuate protein translation in SY5Y‐APPSw human neuroblastoma cells." (PMID 33788386, 2021).
Sepsis (3 papers, 2014 to 2024). Sepsis is defined as life-threatening organ dysfunction caused by a dysregulated host response to infection. "The sepsis-induced increase in eEF2 phosphorylation in muscle of WT mice was consistent with the reduction in mTOR activity and global protein synthesis observed in these animals." (PMID 24945486, 2014). "Sepsis increased eEF2 phosphorylation 60% in muscle from WT mice." (PMID 24945486, 2014). "However, in contrast to WT mice, sepsis did not further increase eEF2 phosphorylation in DKO mice." (PMID 24945486, 2014).
cervical cancer (2 papers, 2022 to 2023). A primary or metastatic malignant neoplasm involving the cervix. "Another study discovered that the YTHDF1/eEF-2 complex and IGF2BP3 increase the translation elongation and mRNA stability of pyruvate dehydrogenase kinase 4 to control glycolysis in cervical cancer cells." (PMID 36091006, 2022).
colitis (2 papers, 2017 to 2023). Inflammation of the colon. "TbP and Eef2 were shown to be the reference genes of choice for RT-qPCR data normalization when assessing colonic inflammation using the DSS-experimental colitis model." (PMID 28186172, 2017).
dementia (2 papers, 2018 to 2025). Loss of intellectual abilities interfering with an individual's social and occupational functions. "Previous reports, including our own published data, show that phosphorylation of eEF2 (p-eEF2, T56) is strongly increased in postmortem hippocampus and mesial temporal cortex in AD, the major neurodegenerative disease with dementia." (PMID 29961428, 2018). "Our findings present direct evidence supporting the pathophysiological role of aberrant eEF2K/eEF2 signaling in brain function and help provide insight into novel mechanisms and therapeutic avenues for neuronal diseases characterized by dementia and neuropsychiatric symptoms." (PMID 41392093, 2025).
developmental delay (2 papers, 2022 to 2025). "In this article, we present an eight-year-old boy with developmental delay and cerebellar symptoms who was found to have a de novo eukaryotic elongation factor 2 (EEF2) mutation on genetic testing." (PMID 35847164, 2022). "However, three pediatric patients with de novo EEF2 mutations were recently discovered, presenting with noncerebellar symptoms such as syndactyly, developmental delay, and behavioral issues." (PMID 35847164, 2022).
epilepsies (2 papers, 2021 to 2022). "Furthermore, the hippocampal eEF2 phosphorylation levels under basal conditions were reduced in mice exhibiting epilepsy and abnormally enhanced excitability in CA3 pyramidal neurons." (PMID 34526091, 2021). "Chronically increased neuronal excitation might lead to the excitatory synapse dependent activation of the eEF2K/eEF2 pathway and the subsequent dampening of the GABAergic synapses would further increase network activity, thereby aggravating the epilepsies in the Scn1a ± mice." (PMID 34980259, 2022).
esophageal squamous cell carcinoma (2 papers, 2014 to 2023). Esophageal squamous cell carcinoma (ESCC) is a type of esophageal carcinoma (EC) that can affect any part of the esophagus, but is usually located in the upper or middle third. "In the present study, we utilized tissue array to evaluate eEF2 protein expression and clinical significance in esophageal squamous cell carcinoma (ESCC)." (PMID 37088855, 2023).
intervertebral disc degeneration (2 papers, 2019). "EEF2, also selected during Beta-based model development, has been shown to play a role in intervertebral disc degeneration and is the target of the OA-associated microRNA-143-5p43." (PMID 31727952, 2019).
osteosarcoma (2 papers, 2023 to 2024). A usually aggressive malignant bone-forming mesenchymal neoplasm, predominantly affecting adolescents and young adults. "We identified that TSN was a potential inhibitor of eEF2, although it was reported that TSN could bind with STAT3 in osteosarcoma tumor." (PMID 37088855, 2023).